KRAS (KRas proto-oncogene, GTPase)
Diseases named in the same sentence as KRAS in open-access papers (continued):
Sharing a sentence is not in itself a finding about the gene and the disease.
ovarian carcinoma (continued). "Moreover, Sirt1 is found to be coordinately overexpressed with KRAS and likely participates in the pathogenesis of endometriosis-associated ovarian cancer." (PMID 34955846, 2021). "Additionally, higher expression of KRAS was also significantly associated with lower OS of ovarian cancer patients." (PMID 32626534, 2020). "Consequently, in our study, four KRAS-mutated cases (codon 12) died in 3–4 months after diagnosed of ovarian cancer." (PMID 33207545, 2020). "Interestingly, ovarian carcinoma patients with the KRAS G12V mutation appeared to have shorter overall survival than those without this mutation." (PMID 32486141, 2020). "Hence, it is very important to focus on KRAS mutations for the development of future therapies to treat lung and ovarian cancer." (PMID 33060649, 2020). "However, in contrast to the co-activation of AKT and STAT3 signaling in PIK3R1 loss ovarian cancer cells, the molecular rationale underlying the synergism in the KRAS mutant gastric cancer cells is the activation of STAT3 upon inhibition of PI3K signaling." (PMID 30755611, 2019). "This difference in mutational status explains the difference in KRAS community scores between pancreatic and ovarian cancers more accurately than cell lineage and stands in contrast to the NF1 gene community example where both a specific lineage and mutational status were important characteristics." (PMID 30573688, 2018). "Also noteworthy was the fact that 19 ovarian cancer patients were KRAS mutated demonstrating an efficient way to overcome this aggressive mutation." (PMID 28008141, 2017). "In ovarian cancer, the KRAS-variant predicts poor outcome due to platinum resistance." (PMID 24732316, 2014). "Mutations in the KRAS gene are one of the most frequent genetic abnormalities in ovarian cancer, and are more frequently present in carcinoma of a lower grade and International Federation of Gynecology and Obstetrics (FIGO) stage, and in lesions of a mucinous histotype." (PMID 24936796, 2014). "Moreover, type II ovarian carcinoma cells with concomitant KRAS amplification and mutation exhibited dramatic growth reduction following treatment with the MEK inhibitor PD0325901." (PMID 23820584, 2013). "Somatic mutations in KRAS were identified in 3 (5.8%) of 51 type II ovarian carcinomas." (PMID 23820584, 2013). "Thus, inactivation of ERK1/2 resulted in marked growth inhibition in ovarian carcinomas with amplification/mutations in KRAS in comparison with only a slight effect on wild-type tumors." (PMID 23820584, 2013). "Interestingly, both responders of the ovarian cancer subset had a simultaneous MAPK pathway mutation (one each in KRAS and BRAF)." (PMID 24036443, 2013). "Activating KRAS mutations are common in ovarian carcinomas of low histological grade, less advanced clinical stage and mucinous histological subtype, and form part of the distinct molecular alterations associated with type I tumors in the dualistic model of ovarian carcinogenesis." (PMID 23800114, 2013). "The finding that the prevalence of the KRAS-variant is significantly higher in women tested within two years of ovarian cancer diagnosis likely reflects the fact that these patients have worse ovarian cancer specific survival and a higher risk for interim death over time." (PMID 22662244, 2012). "The KRAS-variant was most enriched in women who were tested within two years of their ovarian cancer diagnosis, likely reflecting the increased risk of interim death of KRAS-variant positive ovarian cancer patients with longer accrual times." (PMID 22662244, 2012). "Because the KRAS-variant predicts poor ovarian cancer specific survival in uninformative patients, we investigated the association of the prevalence of the KRAS-variant and time between ovarian cancer diagnosis and study recruitment for uninformative patients with available information (n = 82)." (PMID 22662244, 2012).
ovarian carcinoma (continued). "Furthermore, the KRAS-variant was found in 35% of uninformative double primary patients diagnosed with ovarian cancer post-menopausally, and was significantly associated with uninformative double primary patients with a positive family history." (PMID 22662244, 2012). "The presence of the KRAS variant was likewise associated with poor prognosis in head and neck squamous cell carcinoma as well as with the 2.5-fold increased risk of developing epithelial ovarian cancer (EOC)." (PMID 22436609, 2012). "The KRAS-variant is significantly associated with uninformative breast and ovarian cancer patients." (PMID 22662244, 2012). "We additionally found a significant association of the KRAS-variant with age of ovarian cancer diagnosis, with 34.9% of women diagnosed with ovarian cancer postmenopausally having the KRAS-variant (n = 22/63), compared to only 12.5% of women diagnosed with ovarian cancer premenopausally (n = 3/24)." (PMID 22662244, 2012). "The KRAS-variant was also significantly enriched in uninformative patients who developed more then two primary cancers, being found in 48% of women with two breast primaries plus ovarian cancer or with triple primary cancers." (PMID 22662244, 2012). "In addition, we analyzed associations between exon 9 PIK3CA and KRAS mutations and between exon 20 PIK3CA and KRAS mutations in colorectal and ovarian cancers, which were the two largest disease subgroups." (PMID 21829508, 2011). "Of the genes found to be regulated during the estrous cycle and mutated in cancers, have been described in ovarian cancer including KRAS which hasan established role in ovarian cancer, particularly in Type I tumors, that islow-grade ovarian cancer and low malignant potential tumors." (PMID 21423607, 2011). "Recently, a low-density biochip assay, designed for the sensitive detection of 10 mutations in codons 12 and 13 of the KRAS gene (Val12, Asp12, Leu12, Ser12, Ala12, Ile12, Cys12, Arg12, Cys13, Asp13) has successfully been introduced to KRAS mutation screening in ovarian cancer." (PMID 22272089, 2011). "Mutations in the KRAS gene are one of the most frequent genetic abnormalities in ovarian carcinoma." (PMID 19358724, 2009). "In ovarian cancer, KRAS mutations belong to the most frequently observed abnormalities." (PMID 19358724, 2009). "SKOV3 and A2780 showed weak expression of ERK1/2.These results suggest that activation of ERK1/2 may depend on KRAS/BRAF mutation in ovarian cancer cells." (PMID 19018267, 2008). "Thus, inactivation of ERK1/2 results in marked growth inhibition in ovarian carcinomas with mutations in KRAS or BRAF in comparison with only a modest effect on wild-type tumours." (PMID 19018267, 2008). "Therefore, we recommend that in further clinical trials of MEK inhibitors for ovarian cancer, patients are stratified on the basis of KRAS/BRAF mutational status." (PMID 19018267, 2008). "Three ovarian cancer cell lines harboured either KRAS or BRAF mutations." (PMID 19018267, 2008). "Therefore, further studies are needed to clarify the effects of other BRAF mutations in ovarian cancer, and to completely describe the mutation profile of KRAS-BRAF signalling in established ovarian cancer cell lines." (PMID 19018267, 2008). "Therefore, CI-1040 has the potential to be developed into a drug for the treatment of ovarian carcinomas in patients with either KRAS or BRAF mutations." (PMID 19018267, 2008). "Somatic mutations of KRAS were identified in 8 (13.7%) out of 58 ovarian carcinomas." (PMID 19018267, 2008). "In addition, our observations have an important therapeutic implication in ovarian cancer patients with KRAS or BRAF mutations." (PMID 19018267, 2008).
ovarian carcinoma (continued). "It was found that CB-839 could synergize with other anticancer drugs to exert beneficial therapeutic effects, and KRAS mutation led to enhanced glucose and glutamine metabolism in ovarian cancer cells, which was better inhibited by the combination of metformin and CB-839." (PMID 40598593, 2025). "Interestingly, we found that MI-136 treatment induced downregulation of KRAS signalling, whose constitutive activation is typically associated with low-grade ovarian carcinoma, endometrioid and mucinous ovarian tumours since these OC subtypes usually bear KRAS activating mutations." (PMID 36333801, 2022). "While genomic studies have shown that the KRAS pathway plays a key role in several gynecological cancers, the exact mechanism of tumorigenesis involving KRAS mutations has been mostly investigated in studies focusing on endometrial cancer and low-grade ovarian cancer." (PMID 33801965, 2021). "Thus, targeting the SL partner gene CDK1 in ovarian cancer patients carrying a KRAS mutation could be a good choice in anticancer drug research and development." (PMID 29855504, 2018). "The prevalence of the KRAS-variant was 38.5% (n = 20/52) in patients recruited within two years of their ovarian cancer diagnosis, which was significantly higher than the prevalence in patients recruited more than 2 years after their ovarian cancer diagnosis (16.7%, n = 5/30, p<0.048 by Exact test)." (PMID 22662244, 2012). "Because prior reports have found that the KRAS-variant is rarely associated with premenopausal ovarian cancer (less then 52 years of age), we next evaluated the association of the KRAS-variant with age of ovarian cancer development in uninformative double primary patients." (PMID 22662244, 2012). "In addition, the KRAS-variant was significantly associated with BRCA-uninformative patients who developed ovarian cancer post-menopausally (as estimated by age >52 years), and with BRCA-uninformative patients with a positive family history of breast or ovarian cancer." (PMID 22662244, 2012). "Finally, the KRAS-variant was significantly associated with an increased risk of developing a third, independent cancer in addition to breast and ovarian cancer, being found in 43.8% of patients with triple primary cancers, most of whom had uninformative BRCA testing." (PMID 22662244, 2012). "KRAS is frequently amplified or overexpressed in ovarian cancer and represents a potential therapeutic target for overcoming chemoresistance." (PMID 41683990, 2026). "The effectiveness of KRAS and NOXA as diagnostic biomarkers at the genetic level was assessed for their diagnostic ability to distinguish between ovarian cancer patients and the healthy control group." (PMID 40913040, 2025). "Exome sequencing revealed that 79% of lesions (EC and/or DIE) carried mutations, with 26% involving ARID1A, PIK3CA, KRAS, or PPP2R1A, among which PIK3CA and KRAS are frequently altered in ovarian cancer." (PMID 41465243, 2025). "The obtained data from proteomic analysis showed a statistically significant increase in KRAS protein in ovarian cancer patients as well as in patients with more aggressive tumor features." (PMID 40913040, 2025). "The clustering of KRAS and ADAMTS19, genes known to be involved in endometriosis-associated ovarian cancer, also provides a molecular foundation for potential malignant transformation, emphasizing the disease’s multifaceted impact." (PMID 41516028, 2025). "Our method also determined the VAF of ovarian cancer‐related sites (KRAS‐G12R, NRAS‐G12C, and BRAF‐V600E) in clinical tissue and blood samples, enabling the discrimination between ovarian cancer patients and healthy volunteers." (PMID 39903775, 2025). "Specifically, KRAS transcriptomic levels serve as a reliable discriminator of ovarian cancer progression." (PMID 40913040, 2025).
ovarian carcinoma (continued). "One of the MEK inhibitors, trametinib, combined with the PI3K inhibitor, buparlisib, shows promising antitumor activity in KRAS-mutant ovarian cancer patients." (PMID 40862711, 2025). "Recently, the catalytic FAK inhibitor defactinib was granted accelerated approval by the FDA for the treatment of KRAS-mutant low grade serious ovarian cancer (LGSOC) in combination with the RAF/MEK clamp avutometinib." (PMID 41019359, 2025). "A significant difference in the KRAS staining suggests the potentially transformative role of KRAS in the pathophysiology of ovarian cancer conditions." (PMID 38390896, 2024). "This review also addresses the paradoxical better prognosis linked to KRAS and BRAF mutations in ovarian cancer." (PMID 38391958, 2024). "KRAS, which is one of the most frequently mutated oncogenes from the RAS family, plays a pivotal role in ovarian cancer metabolism by regulating the TCA cycle." (PMID 37110218, 2023). "Circulating tumor DNA (ctDNA) allows non-invasive detection of ovarian cancer mutations, such as PIK3CA and KRAS, with potential as diagnostic and prognostic markers in liquid biopsy." (PMID 37629546, 2023). "Recurrent, platinum-sensitive, KRAS wild-type recurrent ovarian cancer.Chemotherapy (carboplatin and PLD or gemcitabine) alone in combination with Panitumumab.Randomised, open-label." (PMID 35020853, 2022). "The KM plotter tool was used to explore the prognostic value of KRAS expression in ovarian cancer patients and to establish a correlation between gene expression and patient survival." (PMID 36142803, 2022). "An increase in the expression level of mRNA and protein in women with ovarian cancer was observed for KRAS, c-FOS, and EGFR." (PMID 35807169, 2022). "An increase in the expression level of mRNA and protein in women with ovarian cancer was observed for KRAS, c-FOS, PUMA, and EGFR." (PMID 35807169, 2022). "BRAF V600E and PIK3CA E542K were predominantly associated with thyroid cancer and ovarian cancer, respectively, whereas ERBB2 amplification, BRCA1/2 variant, and KRAS G12C were widely detected across various cancer types." (PMID 36088851, 2022). "Platinum-resistant, KRAS(Kirsten rat sarcoma virus) wild-type ovarian cancer.Chemotherapy (PDL) with panitumumab.Single treatment arm." (PMID 35020853, 2022). "This phenomenon was also observed in our previous studies wherein oncolytic VV with deletions of both VGF and O1 genes achieved tumor-selective replication in mouse models with xenograft tumors derived from ovarian carcinoma with wild-type KRAS." (PMID 33922406, 2021).
ovarian carcinoma (continued). "In a phase Ib clinical trial of patients with selected advanced solid tumors, combination of the pan-PI3K inhibitor BKM120 and the MEK1/2 inhibitor trametinib displayed promising anti-tumor activities to patients with KRAS-mutant ovarian cancer." (PMID 33407478, 2021). "KRAS mutant ovarian cancer patients show responses to MEK inhibitors, however the predictive value of RAS mutations differed between studies." (PMID 33947352, 2021). "The conclusions of their research indicate a significant role of KRAS and SIRT1 in the pathogenesis of endometriosis as well as ovarian cancer associated with endometriosis." (PMID 33435147, 2021). "The observed increase in SIRT1 expression was related to the nuclear form and was correlated with the expression of KRAS in endometriosis-related ovarian cancer." (PMID 33435147, 2021). "In parallel, combined treatment with VS-6766/CH5126766 and AXL inhibitor (bemcentinib) has provided a stronger blockage of tumor growth in KRAS-mutant ovarian cancer cells with overexpressed AXL." (PMID 34946644, 2021). "For these reasons, selectively targeting the KRAS G12V mutant is among the highest priorities of ovarian cancer therapy." (PMID 32486141, 2020). "Promising antitumor activity against KRAS (especially G12V) mutant ovarian cancers was seen, including a response rate of 29% (one complete and five partial responses), disease control rate of 76%, and median progression‐free survival of 7 months." (PMID 31958897, 2020). "KRAS mutations occur in 3.7–36.4% of endometrioid ovarian cancers, though therapies targeting KRAS have rarely been used to treat ovarian cancer." (PMID 33060649, 2020). "In ovarian cancer, miR-613 suppressed cell proliferation, invasion and colony formation by targeting KRAS expression." (PMID 32592365, 2020). "On the other hand, given that RAS mutant tumors are usually resistant to PARP inhibitors and other anticancer drugs, the inhibition of MEK and ERK can reverse PARP inhibitor resistance in KRAS mutant tumors, including ovarian cancer." (PMID 32429466, 2020). "Less commonly, the oncogenic activity of KRAS can be increased by amplification in ovarian cancer and LUSC." (PMID 31379928, 2019). "Recent studies in lung and ovarian cancer suggest that KRAS activation (KRASact) can influence histological phenotype." (PMID 31111275, 2019). "In this study, we assessed the role of the KRAS oncogene in ovarian cancer cell dissemination, focusing on the stability of cells in spheroid condition, as well as the modulation of intracellular signaling following spheroid transformation." (PMID 30509235, 2018). "We showed that KRAS promotes ovarian cancer cell dissemination by stabilizing spheroid formation and that the MEK pathway is responsible for stabilized spheroid formation." (PMID 30509235, 2018). "Our data indicated that KRAS promoted ovarian cancer dissemination by stabilizing spheroid formation and that the MEK pathway is important for stabilized spheroid formation." (PMID 30509235, 2018). "In this study, we demonstrated that KRAS promotes ovarian cancer cell dissemination by stabilizing spheroid formation and that the MEK pathway is responsible for stabilized spheroid formation." (PMID 30509235, 2018).